ACVRL1 (activin A receptor like type 1)
Description:
Type I receptor for TGF-beta family ligands BMP9/GDF2 and BMP10 and important regulator of normal blood vessel development. On ligand binding, forms a receptor complex consisting of two type II and two type I transmembrane serine/threonine kinases. Type II receptors phosphorylate and activate type I receptors which autophosphorylate, then bind and activate SMAD transcriptional regulators. May bind activin as well.
Synonyms: ALK-1; SKR3; TSR-I; ACVRLK1; ALK1; HHT2; HHT; ORW2
Tractability: Small molecule: a drug acting on it is in phase 2 or 3 trials; a structure with a bound ligand is known; a high-quality ligand is known; it has a high-quality binding pocket; it belongs to a druggable protein family. Antibody: a drug acting on it is in phase 2 or 3 trials; UniProt places it where antibodies can reach, with high confidence; its Gene Ontology location is reachable by antibodies, with high confidence; UniProt predicts a signal peptide or a membrane-spanning region. PROTAC: a small molecule that binds it is known.
Target class: Enzyme; TKL protein kinase group; TKL protein kinase STKR family; TKL protein kinase STKR Type 1 subfamily; Protein Kinase; Kinase
Chemical probes: M4K2234 (high quality), MU1700 (high quality)
Gene: Protein-coding gene on chromosome 12 (51,906,908 to 51,923,361, forward strand). Ensembl gene ENSG00000139567.
Subcellular location: Cell membrane
Pathways (Reactome):
Signal Transduction: Signaling by BMP
Gene Ontology:
Molecular function: activin binding; activin receptor activity, type I; ATP binding; BMP receptor activity; protein binding; protein kinase binding; protein serine/threonine kinase activity; SMAD binding; transforming growth factor beta binding; transforming growth factor beta receptor activity; transforming growth factor beta receptor activity, type I; transmembrane receptor protein serine/threonine kinase activity; protein kinase activity
Biological process: angiogenesis; blood circulation; BMP signaling pathway; cellular response to BMP stimulus; cellular response to transforming growth factor beta stimulus; endothelial tube morphogenesis; lymphatic endothelial cell differentiation; negative regulation of blood vessel endothelial cell migration; negative regulation of cell adhesion; negative regulation of cell growth; negative regulation of cell migration; negative regulation of cell population proliferation; negative regulation of endothelial cell migration; negative regulation of focal adhesion assembly; positive regulation of bicellular tight junction assembly; positive regulation of BMP signaling pathway; positive regulation of DNA-templated transcription; positive regulation of epithelial cell differentiation; positive regulation of Notch signaling pathway; positive regulation of SMAD protein signal transduction; positive regulation of transcription by RNA polymerase II; regulation of blood pressure; regulation of DNA-templated transcription; signal transduction; transforming growth factor beta receptor signaling pathway; and 32 more
Cellular component: cell surface; plasma membrane; BMP receptor complex; membrane
Genetic constraint (gnomAD): Loss-of-function variants: 21 observed, 53.1 expected, observed/expected ratio (o/e) 0.4, 90% interval 0.28 to 0.57. The upper end of that interval is the gene's LOEUF score, 0.57, which puts it in group 2 of 6, group 1 being the genes least tolerant of losing a copy. Missense variants: 451 observed, 678.58 expected, observed/expected ratio (o/e) 0.66, 90% interval 0.61 to 0.72. Synonymous variants: 288 observed, 282.24 expected, observed/expected ratio (o/e) 1.02, 90% interval 0.93 to 1.12.
Gene-disease validity (ClinGen):
ClinGen rates the evidence that ACVRL1 causes each of these diseases.
telangiectasia, hereditary hemorrhagic, type 2 (autosomal dominant): Definitive. Any hereditary hemorrhagic telangiectasia in which the cause of the disease is a mutation in the ACVRL1 gene.
Homologues: Orthologues: chimpanzee ACVRL1 (100% identical), macaque ACVRL1 (99% identical), dog ACVRL1 (93% identical), pig ACVRL1 (92% identical), rat Acvrl1 (90% identical), mouse Acvrl1 (89% identical), guinea pig ACVRL1 (86% identical), rabbit ACVRL1 (59% identical), zebrafish acvr1l (58% identical), tropical clawed frog acvrl1 (58% identical), zebrafish acvrl1 (55% identical), Drosophila melanogaster sax (50% identical), and 7 more. Paralogues in human: ACVR1 (60% identical), ACVR1B (46% identical), TGFBR1 (46% identical), BMPR1A (45% identical), ACVR1C (44% identical), BMPR1B (44% identical), ACVR2A (28% identical), TGFBR2 (28% identical), ACVR2B (28% identical), BMPR2 (28% identical), AMHR2 (24% identical).
Diseases named in the same sentence as ACVRL1 in open-access papers:
ACVRL1 is named in the same sentence as 97 diseases in open-access papers, as found by Europe PMC text mining. Sharing a sentence is not in itself a finding about the gene and the disease. The quoted sentences say what the papers report.
hereditary hemorrhagic telangiectasia (106 papers, 2008 to 2026). A disorder of angiogenesis leading to arteriovenous dilatations: cutaneo-mucosal hemorrhagic telangiectasias and visceral shunting. "Hereditary Hemorrhagic Telangiectasia (HHT) is a rare vascular disease mainly caused by pathogenic mutations in ACVRL1 and ENG genes." (PMID 40681766, 2025). "Mutations in ACVRL1 (or endoglin) can cause the vascular disease hereditary hemorrhagic telangiectasia type 2 (HHT2), which is associated with abnormal blood vessel structures and increased risk of bleedings." (PMID 41378712, 2025). "A disease-causing mutation in the ACVRL1 gene (exon 9, chromosome 12) was detected, establishing the diagnosis of Hereditary Hemorrhagic Telangiectasia type 2 (HHT-2)." (PMID 41025027, 2025). "The associations with these genes are interesting because ACVRL1 mutations have previously been reported in primary PH cases with hereditary hemorrhagic telangiectasia." (PMID 38732015, 2024). "The combined phenotype occurs because SMAD4 mediates signalling through the BMPR1A receptor implicated in juvenile polyposis (JP, OMIM174900), and ACVRL1/Endoglin signalling involved in Hereditary Haemorrhagic Telangiectasia (HHT, OMIM187300 &600376)." (PMID 38627541, 2024). "Hereditary hemorrhagic telangiectasia (HHT) type 2 is an autosomal dominant disease in which one allele of the ACVRL1 gene is mutated." (PMID 37371070, 2023). "Reduced ENG or ACVRL1 activity, owing to loss-of-function mutations, leads to the human disease hereditary haemorrhagic telangiectasia (HHT)." (PMID 36861761, 2023). "Mutations in ENG and ACVRL1 lead to similar phenotype and account for 85% of hereditary hemorrhagic telangiectasias." (PMID 35281255, 2022). "The co-factors of BMPR-II endoglin (ENG) and activin receptor like kinase 1 (ACVRL1) are predominantly altered in hereditary haemorrhagic telangiectasia associated PAH." (PMID 35346192, 2022). "Here we describe a case of hereditary hemorrhagic telangiectasia complicated with pulmonary arterial hypertension as a result of an ACVRL1 mutation." (PMID 35232468, 2022). "Germline mutations of ACVRL1 also cause hereditary hemorrhagic telangiectasia, a dominant autosomal vascular dysplasia, and PH is recognized as a severe complication of this disease." (PMID 34702814, 2021). "It has been reported that ACVRL1 mutations in hereditary hemorrhagic telangiectasia led to a loss of function." (PMID 34702814, 2021). "Our first family has four affected individuals with hereditary hemorrhagic telangiectasia, and all of them have a novel, heterozygous, likely pathogenic NM_000020.2(ACVRL1): c.1298C>T (p.Pro433Leu) variation." (PMID 31594285, 2019). "In some families with hereditary hemorrhagic telangiectasia type 2 and pulmonary arterial hypertension, variants in the ACVRL1 gene have been reported." (PMID 26398936, 2015). "Patients who are heterozygous for loss of function mutations in ACVRL1 develop the vascular disorder Hereditary Haemorrhagic Telangiectasia (HHT) type 2." (PMID 24896812, 2014). "Girerd and collegues described this for patients with familial PAH and hereditary hemorrhagic telangiectasia carrying a mutation in the ACVRL1 gene." (PMID 21801371, 2011). "Also down‐regulated are ACVRL1—mutations in which cause vessel malformations in hereditary haemorrhagic telangiectasia 46—endothelin 1 (EDN1), which encodes vasoconstrictive peptides, and CCL2, which has chemotactic activity for monocytes and basophils." (PMID 28631889, 2017). "This case presents a singular confluence of hepatocellular carcinoma (HCC), type 2 hereditary hemorrhagic telangiectasia (HHT) with an ACVRL1 mutation, and a history of schistosomal liver disease—a combination reported only sporadically worldwide." (PMID 41583846, 2025). "ACVRL1 or ENG genetic variants have been found in patients with hereditary hemorrhagic telangiectasia (HHT) combined with PAH." (PMID 35811711, 2022).
hereditary hemorrhagic telangiectasia (continued). "That is, hereditary hemorrhagic telangiectasia (or HHT) caused by mutations in ACVRL1 and ENG, involves arteriovenous malformations mainly affecting the lungs and liver; or, mutations in BMPR2 may lead to pulmonary hypertension with no impairment of the endothelium in other organs." (PMID 35163400, 2022). "The mutations in ACVRL1 or ENG genes primarily lead to PAH associated with hereditary hemorrhagic telangiectasia (HHT), which is a rare autosomal dominantly genetic disease." (PMID 36506323, 2022). "Hereditary hemorrhagic telangiectasia (HHT) is an autosomal dominant disorder which is associated with severe abnormalities in the microvascular network and linked to mutations in ACVRL1 and ENG genes." (PMID 35440116, 2022). "Hereditary hemorrhagic telangiectasia (HHT) gene variants in the activin receptor-like kinase 1 (ACVRL1) and endoglin (ENG) have been identified in PAH patients." (PMID 31382961, 2019). "Hereditary hemorrhagic telangiectasia (HHT) is caused by mutations in endoglin or activin receptor-like kinase-1 (ACVRL1/ALK1) genes and is an autosomal dominant vascular disorder." (PMID 30406106, 2018). "The 24 patients receiving elective surgery were aged 17–80 years (mean 39 years), 11 (46%) were male, and 17 had confirmed hereditary hemorrhagic telangiectasia (HHT) spanning ACVRL1, ENG and SMAD4 genotypes." (PMID 39777301, 2025). "Intriguingly, mutations in ACVRL1 and ENG are more commonly associated with hereditary hemorrhagic telangiectasia (HHT) than PAH." (PMID 35434863, 2023). "Hereditary Hemorrhagic Telangiectasia (HHT) is an autosomal dominant, inherited disease, most commonly caused by mutations in the genes encoding endoglin (ENG) or activin A receptor type II-like 1 (ACVRL1, or ALK1)." (PMID 36142926, 2022). "Two patients with hereditary haemorrhagic telangiectasia and PAH carried mutations in ACVRL1 and were classified as HPAH." (PMID 35346192, 2022). "Mutations in Activin receptor-like kinase gene (ACVRL1) encoding the type I receptor ALK1, a major partner in the TGFβ signaling pathway, has been associated with hereditary hemorrhagic telangiectasia type 2 (HHT2, OMIM 600376)." (PMID 35281255, 2022). "All publications from the ACVRL1, ENG and SMAD4 Mutation Databases and publications searched for terms “hereditary hemorrhagic telangiectasia” and “founder” in PubMed and Scopus, respectively, were extracted." (PMID 33919892, 2021). "Hereditary hemorrhagic telangiectasia type 2 (HHT2; OMIM 600376) is caused by mutations in Activin receptor-like kinase gene (ACVRL1) in chromosome 12q13." (PMID 33195419, 2020). "Mutations in ACVRL1 and ENG have been reported in PAH patients and in patients with PH in association with hereditary hemorrhagic telangiectasia (HHT)." (PMID 33256119, 2020). "Additionally, ACVRL1 mutations can lead to hereditary hemorrhagic telangiectasia (HHT), also known as Rendu-Osler-Weber disease, an autosomal dominant inherited disease that results in mucocutaneous telangiectasia and arteriovenous malformations (AVMs)." (PMID 31380118, 2019). "Hereditary hemorrhagic telangiectasia (HHT) is caused by mutations in TGFβ/BMP9 pathway genes, most commonly ENG (OMIM 131195) or ACVRL1 (ALK1, OMIM 601284)." (PMID 29932521, 2018). "Hereditary hemorrhagic telangiectasia (HHT) is an autosomal dominant vascular disorder caused by mutations in ENG, ACVRL1 and SMAD4, which function in regulating the transforming growth factor beta and bone morphogenetic protein signaling pathways." (PMID 27081547, 2015). "Mutations in ACVRL1 gene, located in chromosome 12q13, are directly related to some cases of PAH associated with hereditary hemorrhagic telangiectasia (HHT)." (PMID 24936649, 2014). "Presently, ENG (endoglin) on chromosome 9q33-q34 and ACVRL1 (activin-receptor-like kinase) on chromosome 12q13 are the two genes primarily implicated in the development of Hereditary Hemorrhagic Telangiectasia (HHT)." (PMID 19508727, 2009).
hereditary hemorrhagic telangiectasia (continued). "Hereditary Hemorrhagic Telangiectasia (HHT) is an autosomal dominant and age-dependent vascular disorder characterised mainly by mutations in the Endoglin (ENG) or activin receptor-like kinase-1 (ALK1, ACVRL1) genes." (PMID 18673552, 2008). "Hereditary hemorrhagic telangiectasia (HHT), a genetic disorder may be caused by mutations in genes such as ENG (encoding endoglin) or ACVRL1 (ALK1), and less commonly SMAD4, is one condition that predisposes individuals to multiple AVMs." (PMID 41555917, 2025). "Interestingly, mutations in GDF2, as well as in ACVRL1, ENG and SMAD4 are also known to be causal of hereditary haemorrhagic telangiectasia (HHT)." (PMID 41222740, 2025). "Other, less frequent variants were related to HNF1A-maturity onset of diabetes of the young, MODY, (n = 7, 0.18%); HFE-related haemochromatosis (n = 2, 0.05%); ACVRL1-hereditary haemorrhagic telangiectasia (n = 2, 0.05%); and ATP7B–Wilson disease (n = 1, 0.03%)." (PMID 40332002, 2025). "ACVRL1 is the pathogenic gene of type 2 hereditary hemorrhagic telangiectasia (HHT2), and there’s no NVM reported to be associated with ACVRL1 mutation." (PMID 37120586, 2023). "Hereditary haemorrhagic telangiectasia (HHT) is an autosomal dominant multisystem vascular dysplasia arising from a single heterozygous loss-of-function variant (“mutation”), usually in ENG, ACVRL1, or SMAD4." (PMID 38137783, 2023). "Variants in two other genes in the transforming growth factor-beta (TGF-β) superfamily, activin A receptor type II-like 1 (ACVRL1), and endoglin (ENG) contribute to ~ 0.8% of PAH cases, especially PAH associated with hereditary hemorrhagic telangiectasia (APAH-HHT)." (PMID 33971972, 2021). "Although the majority of BAVMs arise sporadically, they also occur in patients with Hereditary Hemorrhagic Telangiectasia (HHT), a Mendelian disorder inherited in an autosomal dominant fashion and caused by mutations in one of three genes (ACVRL1, ENG and SMAD4) in the TGFβ signaling pathway." (PMID 24098321, 2013). "Dominant causes included 22q deletion syndrome, DYNC1H1, SCN3A, and hereditary hemorrhagic telangiectasia (HHT) genes, ACVRL1 and ENG." (PMID 41670011, 2026). "Hereditary hemorrhagic telangiectasia (HHT) is an autosomal dominant vascular disorder caused by pathogenic variants in ENG (HHT1) and ACVRL1 (HHT2), with distinct phenotypic expressions." (PMID 40648782, 2025). "Hereditary hemorrhagic telangiectasia (HHT), which is caused by pathogenic variants in genes such as ENG (endoglin), ACVRL1 (ALK1), and less commonly SMAD4, is one such condition that predisposes individuals to multiple AVMs." (PMID 41555917, 2025). "Additionally, mutations in BMP9 or the genes encoding BMP‐9/‐10 receptors, ACVRL1 (encoding ALK1) and ENG (encoding endoglin), lead to hereditary hemorrhagic telangiectasia (HHT), a rare genetic disease that is characterized by arteriovenous malformations (AVMs) and internal bleeding." (PMID 39921464, 2025). "In hereditary hemorrhagic telangiectasia (HHT), mutations in ENG or ACVRL1 are frequently observed, while SMAD4 mutations affect a small percentage of patients." (PMID 38673717, 2024). "Hereditary hemorrhagic telangiectasia (HHT) is a rare inherited disease due to heterozygous loss-of-function mutations on the BMP9/10 pathway (ENG, ACVRL1 or MADH4 mainly)." (PMID 38143764, 2023). "For example, it classified 89% of intronic non-canonical splice-altering variants in ACVRL1, a gene that has well-characterized intronic splice-altering variants that cause Hereditary Hemorrhagic Telangiectasia (HHT2 [MIM: 600376]), with constraint scores at or above 0.88." (PMID 36376793, 2022). "Mutations in the ENG and ACVRL1 genes (encoding for ENG and ALK1) cause Hereditary Hemorrhagic Telangiectasia (HHT), which is a genetic form of AVM development." (PMID 33716786, 2021).